NAV3 (neuron navigator 3)
Diseases named in the same sentence as NAV3 in open-access papers (continued):
Sharing a sentence is not in itself a finding about the gene and the disease.
tumor (continued). "However, our findings show that NAV3 is re‐expressed in migrating cells and its overexpression in fact promotes mesenchymal invasive behavior, which challenges its conventional classification as a tumor suppressor." (PMID 39097525, 2025). "NAV3 is a helicase and it was recently shown that a similar gene, the helicase-like transcription factor (HLTF), can have a dual-type of activity, behaving both as an oncogene and as a tumour suppressor." (PMID 22173670, 2012).
neurodevelopmental disorder (2 papers, 2024 to 2025). A behavioral and cognitive disorder with onset during the developmental period that involves impaired or aberrant development of intellectual, motor, or social functions. "Recently, five bi-allelic and three mono-allelic variants in NAV3 were reported in 12 individuals from eight unrelated families with neurodevelopmental disorder (NDD)." (PMID 39708122, 2025). "Our findings establish the role of NAV3 in neurodevelopmental disorders, and reveal its involvement in neuronal morphogenesis, and neuromuscular responses." (PMID 38977784, 2024).
CNS tumors (1 paper, 2021). "It has been suggested that NAV3 amplifications may improve prognosis for some CNS tumors." (PMID 34106998, 2021).
neurological disorders (1 paper, 2024). "Taken together, our findings support the pivotal function of NAV3 in neuronal morphogenesis and neurological disorders in humans." (PMID 38977784, 2024).
NAV3 also shares sentences with these, for which no sentence is quoted: lung carcinoma (3 papers); adrenal carcinoma (2); Huntington disease (2); lymphoma (2); nervous system tumors (2); amyotrophic lateral sclerosis (1); asthma (1); astrocytoma (1); autoimmune disease (1); chronic fatigue syndrome (1); fibrosarcoma (1); generalized epilepsy (1); hippocampal atrophy (1); infection (1); infectious disease (1); learning disabilities (1); male infertility (1); movement disorder (1); multiple sclerosis (1); mycosis fungoides (1); myxoid liposarcoma (1); neurodegenerative disease (1); oligodendroglioma (1); panic disorder (1); personality disorder (1); Pseudoxanthoma elasticum (1); Sezary syndrome (1); spinocerebellar ataxias (1); squamous cell carcinoma (1); T-cell lymphoma (1).